ASPM (assembly factor for spindle microtubules)
Diseases named in the same sentence as ASPM in open-access papers (continued):
Sharing a sentence is not in itself a finding about the gene and the disease.
glioma (continued). "In an attempt to find potential transcript factors that may play a role in increased ASPM expression in gliomas, we predicted several potential FoxM1 binding sites in ASPM promoter using transcript factor binding site prediction databases." (PMID 32667745, 2020). "Depletion of ASPM suppresses the proliferation of glioma spheres and promotes cell death." (PMID 32667745, 2020). "Yet, the underlying molecular mechanisms that mediate the up‐regulation of ASPM expression in glioma tissues remain unknown." (PMID 32667745, 2020). "ASPM was also considered as a marker for distinguishing stem-like cells from gliomas stromal cells." (PMID 25796627, 2015). "In addition, ASPM promotes glioma malignancy by activating the Wnt/β-Catenin signaling pathway." (PMID 35846118, 2022). "However, whether ASPM is involved in the regulation of the cell cycle of glioma cells remains unclear." (PMID 32667745, 2020). "In addition, down‐regulation of ASPM suppressed the growth of glioma in nude mice." (PMID 32667745, 2020). "Consistent with previous studies, our results also indicated that ASPM is significantly positively correlated with the pathological grade of glioma and poor prognosis of patients, and knockdown of ASPM could inhibit the proliferation of glioma cells." (PMID 32667745, 2020). "However, whether FoxM1 can directly regulate ASPM expression and whether the FoxM1‐ASPM axis contributes to the pathogenesis and progression of gliomas remain largely unclear." (PMID 32667745, 2020). "In this study, we aimed to identify genes related to the pathogenesis and progression and prognosis of gliomas based on GEO data sets and investigate the effects of ASPM on the biological functions of glioma cells, as well as the role of FoxM1 in the up‐regulation of ASPM expression in gliomas." (PMID 32667745, 2020). "In addition, it has been reported that ASPM promotes the ubiquitination modification and inhibits the degradation of CyclinE,26 suggesting that ASPM interference may lead to the cell cycle arrest of glioma cells by regulating the abnormal protein expression at the late G0/G1 phase." (PMID 32667745, 2020). "It was found that ASPM, CCNB2, HSPG2, KLHDC8A and RRM2 mRNA were differentially expressed in glioma tissues of different grades." (PMID 32667745, 2020). "Previous studies have shown that ASPM is upregulated in various malignant tumors including hepatocellular carcinoma (HCC), non-small cell lung cancer, glioblastoma and other high-grade gliomas." (PMID 39594769, 2024). "For example, the MCPH5 gene ASPM is highly expressed in 175 gliomas as compared to three normal brain tissues." (PMID 23472065, 2013). "On the other hand, the function of ASPM in neoplastic cells, particularly gliomas, has not been completely elucidated." (PMID 20142996, 2010).
breast carcinoma (21 papers, 2013 to 2024). "For example, a recent study found that ASPM displayed obvious differential expressions in different breast cancer subtypes, and these expression levels were associated with the clinical outcomes." (PMID 25961039, 2015). "In addition, we further analyzed the effects of death risk factors on breast cancer by univariate/multivariate Cox regression analysis proved that high expression of ASPM can be used as an independent prognostic factor for KIRC and LIHC." (PMID 35515103, 2022). "Commonality with most of the short-listed genes (CENPF, KIF14, NEK2, CKS1B and ASPM) is their positive association with proliferation marker Ki-67, thereby, indicating their possible role in cell cycle related dysregulations and the resultant proliferation of breast cancer cells." (PMID 24147022, 2013). "ASPM is a gene involved in cell division, and recent research shows that it plays an important role in breast cancer (BC)." (PMID 39594769, 2024). "Through the analysis of large-scale genomic datasets, ASPM has been identified as the top upregulated gene in breast cancer (BC), characterized by high proliferation." (PMID 39594769, 2024). "The ASPM gene is upregulated in various tumors, including ovarian cancer, breast cancer, colon cancer, glioblastoma, and BLCA." (PMID 37051591, 2023). "In recent years, an increasing number of studies have shown that ASPM is highly expressed not only in central nervous system tumors, but also in a variety of solid tumors, such as prostate cancer, breast cancer, and bladder cancer." (PMID 35515103, 2022). "In fact, ASPM was previously reported to be over-expressed in HCC, and was highlighted as a biomarker associated with poorer prognosis in HCC and breast cancer." (PMID 34199580, 2021). "Among them, ASPM, CDC20, and TTK were negatively associated with relapse-free survival (RFS) of breast cancer patients using Kaplan Meier survival curves by log-rank test." (PMID 31106147, 2019). "According to the test set (GSE25055) and validation set (GSE426568), three hub genes (ASPM, CDC20, and TTK) were significantly associated with the prognosis of breast cancer patients." (PMID 31106147, 2019). "Previous studies have shown that ASPM plays an essential role in tumorigenesis and the development of numerous types of cancers, including pancreatic and breast cancer and clear cell renal cell carcinoma." (PMID 31889904, 2019). "Our study showed that ASPM, INHBA, NUF2, ORC6, UBE2T and PKMYT1 are associated with cell proliferation, and the expressions of these genes were also elevated in our breast cancer tissue transcriptome." (PMID 31182966, 2019). "There are many candidate genes; CENF, KIF14, DTL, NEK2, CKS1B, ASPM and EXO1 each of which are significantly associated with poor clinical outcome in breast cancer patients." (PMID 25312014, 2014). "The subsequent filtering with the combined p-value <0.005 across 6 datasets, yielded 7 candidate genes ASPM, KIF14, NEK2, DTL, CENPF, CKS1B and EXO1 that are significantly associated with poor clinical outcome of the breast cancer patients." (PMID 24147022, 2013). "ASPM was found to up-regulate in some malignancies, such as breast cancer and gastric cancer." (PMID 32194788, 2020). "Thus, elevated levels of CCNB2 may reflect a functional correlation with ASPM overexpression, which could play a role in the progression of breast carcinoma." (PMID 23282137, 2013). "In line with our studies, other groups reported that ASPM, KIF20A, TPX2, AURKA and KIF2C are among the top 11 up-regulated hub key genes identified as potential breast cancer prognostic biomarkers." (PMID 37835564, 2023). "ASPM expression in TNBC was higher than that in luminal (p < 10-13) and HER2 positive (p < 10-4) breast cancer." (PMID 35515103, 2022). "ASPM and CMYA5 are predicted as novel oncogenes in breast cancer, while ERBB2 is an already well-known oncogene in breast cancer." (PMID 31900418, 2020).
breast carcinoma (continued). "More convincingly, the result of qRT-PCR using breast cancer tissues and matched paracancerous tissues exhibited a significant upregulation of ASPM, CDC20, and TTK in breast cancer compared to paracancerous tissues (P < 0.001)." (PMID 31106147, 2019). "Moreover, our study additionally detected a significant correlation between the expression of the ASPM and CCNB2, and the elevated cytoplasmic CCNB2 protein levels were confirmed to be strongly associated with the short-term disease-specific survival of breast cancer patients." (PMID 25961039, 2015). "While the breast cancer candidacy of CENPF, KIF14, NEK2, DTL, CKS1B, ASPM and EXO1 genes have been identified earlier, there is only one prominent report indicating the candidacy of EXO1 in breast cancers and remains to be investigated." (PMID 24147022, 2013). "Here, we present a validation of the prognostic role of five selected candidate biomarkers (CCNB2, ASPM, KIAA0101, CDCA7, and SLC27A2) included in these gene signatures using an independent breast cancer cohort." (PMID 23282137, 2013). "The purpose of the present study was to investigate the prognostic value of the candidate biomarkers CCNB2, ASPM, CDCA7, KIAA0101, and SLC27A2 in breast cancer." (PMID 23282137, 2013). "In addition, ASPM has been identified as a key gene for HER-2, which is related to the poor prognosis of breast cancer patients." (PMID 37229243, 2023). "Moreover, the expression of ASPM was higher in all different subtypes, including luminal breast cancer, HER2 positive breast cancer, and triple- negative breast cancer (TNBC)." (PMID 35515103, 2022). "Similarly, previous studies had stated that ASPM, CDC20, BUB1B, and CDCA8 expression could be potential poor survival prognostic biomarkers in lung adenocarcinoma, prostate/breast cancer, glioblastoma, respectively." (PMID 36186000, 2022). "In addition, we confirmed that the expression levels of the three genes, ASPM, CDCA8 and KIF2C, were significantly reduced following the knockdown or silencing of FOXM1 based on both microarray data in BT-20 breast cancer cells (GSE2222) and RNA-seq data in MCF-7 breast cancer cells (GSE58626)." (PMID 33667222, 2021).
glioblastoma (21 papers, 2008 to 2024). The most malignant astrocytic tumor (WHO grade IV). "Horvath S adopted WGCNA to detect oncogenic modules and confirm abnormal spindle-like microcephaly-associated protein (ASPM) as a potential molecular target in glioblastoma." (PMID 30382873, 2018). "Increased ASPM mRNA and protein levels were also identified in glioblastoma multiforme (GBM), where they were associated with increasing tumour grade." (PMID 24830737, 2014). "EGFR activation upregulates genes involved in neural stem cell proliferation: one of these genes is ASPM (abnormal spindle-like microcephaly associated) that promotes neuroblast proliferation and symmetric division and is strongly upregulated in glioblastomas." (PMID 18492260, 2008). "S. Horvath used WGCNA to identify several gene co-expression modules and revealed abnormal spindle-like microcephaly-associated protein (ASPM) that might function as a potential molecular target in glioblastoma." (PMID 32296458, 2020). "This method was applied to identify disease-associated genes such as ASPM in glioblastoma." (PMID 22956898, 2012). "ASPM is aberrantly expressed in various tumors, such as glioblastoma, endometrial adenocarcinoma, pancreatic cancer, prostate adenocarcinoma, and ovarian cancer, and is associated with tumor prognosis." (PMID 39445005, 2024). "ASPM expression is upregulated in several cancers, including prostate cancer, glioblastoma, and hepatocellular carcinoma, and increased ASPM expression is associated with tumor progression and poor clinical prognosis." (PMID 36980263, 2023). "As demonstrated in several studies, ASPM contributes cell proliferation and invasive properties of different cancer cells, including prostate cancer, lung squamous cell carcinoma, glioblastoma, pancreatic cancer, and bladder cancer." (PMID 35387319, 2022). "The results are consistent with earlier reports where ASPM facilitates glioblastoma cell growth via regulating G1 restriction point." (PMID 35387319, 2022). "The depletion of ASPM by siRNA results in dramatic proliferation arrest of neural stem cells and glioblastoma cells, supporting ASPM as a potential molecular target in the treatment of glioblastoma." (PMID 34428354, 2021). "ASPM is highly expressed in invasive glioblastoma multiform, and ASPM depletion inhibits the proliferation of glioblastoma cells." (PMID 32742488, 2020). "Increased malignancy at recurrence was identified in all 4 non-glioblastoma patients with concomitant increase of ASPM expression in all of them." (PMID 20142996, 2010). "The report of ASPM knockdown inhibiting glioblastoma cell growth and neural stem cell self-renewal point to proliferative and survival roles for this gene." (PMID 20520718, 2010). "Furthermore, up-regulation of CCNB2 and ASPM was detected in glioblastoma multiforme xenograft tumors and de novo glioblastoma multiforme tumors." (PMID 23282137, 2013). "Inhibition of ASPM inhibits glioblastoma cell growth and neural stem cell proliferation." (PMID 18492260, 2008). "Thus, inhibition of ASPM could prove lethal by severely hampering one of the key signaling pathways of glioblastomas." (PMID 20142996, 2010). "Different studies have shown that ASPM expression correlates with WHO grade of the astrocytic tumors, being higher in glioblastomas and in recurrent tumors." (PMID 34663805, 2021).
prostate carcinoma (21 papers, 2019 to 2025). A carcinoma that arises from epithelial cells of the prostate gland. "A recent study found that ASPM (an abnormal spindle-like microcephaly-associated protein) is a novel Wnt co-activator, which maintains cancer stem cells, such as the phenotype in prostate cancer by exerting Wnt signaling." (PMID 36969009, 2023). "Previous studies have shown that ASPM is highly expressed in ovarian, pancreatic, and prostate cancers and it is significantly associated with a poor prognosis." (PMID 36247089, 2022). "Recent literature reports that ASPM expression disorders are associated with the progression of epithelial ovarian cancer, colorectal cancer, prostate cancer, and hepatocellular carcinoma." (PMID 32047816, 2020). "Recently, emerging evidence has illustrated that ASPM is expressed in malignant tissues and associated with the progression of several tumors, including lung carcinoma, gastric cancer, hepatocellular carcinoma, prostate cancer, and pancreatic ductal adenocarcinoma." (PMID 35387319, 2022). "In a variety of malignant tumors, the expression level of ASPM is significantly elevated, which is closely related to the progression of various tumors, including prostate cancer, lung cancer, bladder cancer, and kidney cancer." (PMID 40979592, 2025). "Accumulating evidence suggests that ASPM is a regulator of cell stemness, it enhances stem cell phenotype in prostate cancer cells by enhancing Wnt/β-catenin signaling, thereby promoting tumor aggressiveness." (PMID 35515103, 2022). "ASPM expression is incrementally up‐regulated in prostate cancer, and the increased expression of ASPM correlates with tumor progression and poor clinical prognosis." (PMID 34428354, 2021). "For instance, ASPM triggers prostate carcinoma stemness and progression through enhancing the Wnt-Dvl-3-beta-catenin pathway." (PMID 34987580, 2021). "The stem cell marker, ASPM, promotes cell proliferation in prostate cancer 30 through the Wnt signaling pathway 28, and CENPF is involved in the formation of the centromere-kinetochore complex and was correlated with poor prognosis in the PDAC cohort of TCGA." (PMID 34326696, 2021). "Recent evidence suggests that ASPM promotes prostate cancer stemness and progression and has important clinical and therapeutic significance." (PMID 32833968, 2020). "ASPM, the novel Wnt co-activator, augments the Wnt-β-catenin signaling to maintain the subpopulation of cancer stem cells in prostate cancer." (PMID 33187219, 2020). "In prostate cancer, higher ASPM expression was observed in tumor tissues compared with adjacent prostate tissues, especially in tumors with advanced stages." (PMID 31106147, 2019). "In prostate cancer, high ASPM expression correlated with tumor progression and predicted poor outcome." (PMID 31816603, 2019). "Notably, recent findings by Tsai’s group demonstrated that ASPM enhances a stem cell phenotype in prostate cancer cells by augmenting Wnt/β-catenin signaling, thereby promoting tumor aggressiveness." (PMID 39594769, 2024). "In additional, ASPM may promote the progression of prostate cancer and hepatocellular carcinoma by enhancing the Wnt/β-catenin signaling pathway." (PMID 37184686, 2023). "Previous studies have reported that increased ASPM expression may predict poor biochemical recurrence-free survival in prostate cancer patients." (PMID 35515103, 2022). "ASPM is a positive regulator of the canonical Wnt/β-catenin signaling and thus promotes cancer stemness and progression in prostate cancer and hepatocellular carcinoma." (PMID 34142045, 2021). "Recent work has identified that ASPM interacts with disheveled-3 (Dvl-3), a cardinal upstream regulator of canonical Wnt signaling, and inhibits its proteasome-dependent degradation, thereby increasing its protein stability and enabling β-catenin transcriptional activity in prostate cancer cells." (PMID 35387319, 2022).
prostate carcinoma (continued). "ASPM binds to disheveled segment polarity protein 3 (DVL-3), a key upstream regulator of canonical Wnt signaling, and prevents it from being degraded by the proteasome, thereby strengthening protein stability and enhancing Wnt-induced β-catenin transcriptional activity in prostate cancer cells." (PMID 36969009, 2023).
hepatocellular carcinoma (18 papers, 2019 to 2024). A malignant tumor that arises from hepatocytes. "The abnormal spindle‐like microcephaly‐associated protein (ASPM) promotes hepatocellular carcinoma progression by activating Wnt/β‐catenin signaling." (PMID 34428354, 2021). "ASPM was highly expressed in the hepatocellular carcinomas and was correlated with metastatic potential and tumor recurrence." (PMID 35387319, 2022). "ASPM high-expression was found in tumor tissues of hepatocellular carcinomas, an observation correlated with increased invasive capacity and high tumor recurrence." (PMID 32742488, 2020). "Previous studies have found that high expression of ASPM is significantly positively correlated with vascular invasion and early metastasis of hepatocellular carcinoma, and its high expression indicates poor prognosis of hepatocellular carcinoma patients." (PMID 32667745, 2020). "In hepatocellular carcinoma, ASPM was suggested to be a novel marker for vascular invasion, early recurrence, and poor prognosis." (PMID 31816603, 2019). "In hepatocellular carcinoma, upregulation of ASPM enhanced the metastatic capability of tumor, which was a marker for vascular invasion, early recurrence, and poor prognosis." (PMID 31106147, 2019). "In prostate and hepatocellular cancers, ASPM promoted the progression and exacerbated the prognosis, which means ASPM might be a novel marker for cancer progression." (PMID 32099532, 2020). "Furthermore, ASPM has also been reported involved in the progression of diverse tumors, including hepatocellular carcinomas, gastric cancer, pancreatic ductal adenocarcinomas, and lung cancer 21-24." (PMID 32742488, 2020). "ASPM overexpression has been recognized as a molecular marker that correlates with heightened invasive and metastatic potential in hepatocellular carcinoma (HCC)." (PMID 38144520, 2023). "Also, recent studies have shown that the expression level of ASPM in hepatocellular carcinoma (HCC) patients is higher than that compared with normal tissues." (PMID 36304312, 2022). "Previous studies showed that ASPM was highly expressed in hepatocellular carcinoma (HCC), and the high expression of ASPM was correlated with poor HCC prognosis." (PMID 35087827, 2021).